MMP9 (matrix metallopeptidase 9)
Diseases named in the same sentence as MMP9 in open-access papers (continued):
Sharing a sentence is not in itself a finding about the gene and the disease.
intracranial hemorrhage (15 papers, 2011 to 2025). Bleeding within the SKULL, including hemorrhages in the brain and the three membranes of MENINGES. "The upregulation of MMP-9 could cause anti-Aβ immunotherapy to result in brain hemorrhages, which in turn contribute to the breakdown of the blood-brain barrier (BBB), while the downregulation of activity and/or expression of MMP-9 could facilitate Aβ elimination across the BBB." (PMID 36674771, 2023). "For example, it was found that astrocytic induction of MMP-9 and edema in brain hemorrhage." (PMID 34067678, 2021). "In our case, the correlation between MMP-9 levels and bleeding is consistent with a key role of MMPs in brain haemorrhage, suggesting that both meningococci and MMPs may have contributed to intracerebral bleeding in the model." (PMID 25551808, 2014). "It has been shown that heparin can produce intracranial hemorrhage dependent of MMP-9 activity." (PMID 21731773, 2011). "It has been also suggested that alteplase may promote intracranial hemorrhage through non-fibrinolytic mechanisms, such as activation of the immune system, neutrophil degranulation and release of matrix metalloproteinase-9 (MMP-9) favoring BBB disruption." (PMID 36756347, 2022).
malaria (15 papers, 2010 to 2021). Malaria is a serious and sometimes fatal disease caused by a parasite that commonly infects a certain type of mosquito which feeds on humans. "Likewise, MMP9, an endopeptidase released by neutrophils and monocytes, is implicated in the pathogenesis of severe malaria." (PMID 34737733, 2021). "With this in mind, the possibility that Pg-FET could interact with the production of MMP-9, an enzyme directly implicated in the pathogenesis of malaria was considered." (PMID 20642847, 2010). "Local MMP2 upregulation has been seen in experimental cerebral malaria, a clinical subphenotype of severe malaria also linked to CD8+ T cell-mediated tissue injury, and MMP9 functional polymorphisms are thought to increase susceptibility to placental malaria." (PMID 33563839, 2021). "Consistently, microarray analysis performed on whole blood from Kenyan children with severe malaria showed P. falciparum activation of the human MMP-9 gene." (PMID 24467887, 2014). "For example, in malaria, activation of MMP-9 was dependent upon the production of TNF and its activation was decrease by anti-TNF treatment." (PMID 25393535, 2014). "Recently matrix metalloproteinase-9 (MMP-9) and its endogenous inhibitor (tissue inhibitor of metalloproteinase-1, TIMP-1) have been implicated in complicated malaria." (PMID 23967215, 2013). "In the present paper the role of HZ and MMP-9 in complicated malaria, as well as their interactions, will be discussed." (PMID 21760809, 2011). "In the last decade, few evidence of direct involvement of MMP-9 in severe malaria has been reported." (PMID 21760809, 2011). "Evidence of the involvement of MMPs in complicated severe malaria has been emerging during the last decade, and HZ-dependent induction of MMP-9 expression and activity has been demonstrated in mononuclear or endothelial cells." (PMID 21760809, 2011). "Activation of the human MMP-9 gene by P. falciparum has been shown in microarray studies on whole blood from children with severe malaria, whereas MMP-9 increases in cerebrospinal fluid levels were not apparent, possibly because of the enzyme's tight association with the extracellular matrix." (PMID 21760809, 2011). "In this way it is attractive to hypothesize that increased TIMP-1 levels are actually protective rather than a risk factor in malaria prognosis, as they could contrast the potentially detrimental effects of nHZ-enhanced MMP-9." (PMID 23967215, 2013). "The present paper will explore the effects of HZ on functions of mononuclear and endothelial cells, focusing on regulation of human MMP-9, which at present among the malaria-related MMPs is the most studied and could be a potential target for adjunctive therapy of complicated severe malaria." (PMID 21760809, 2011). "Among these genes, some were previously shown to play a role in severe malaria, specially CXCL10, ARG1, ATP2B4, and MMP9." (PMID 32801995, 2020). "This is in line with a previous study, in which no significant changes in plasma levels of MMP9 were observed in children with malaria infection compared to malaria negative children." (PMID 31042729, 2019). "HZ-fed human monocytes are functionally compromised, releasing increased amounts of pro-inflammatory molecules, including cytokines, chemokines and cytokine-related proteolytic enzyme Matrix Metalloproteinase-9 (MMP-9), whose role in complicated malaria has been recently suggested." (PMID 22724024, 2012). "Placental malaria did not have any significant effect on MMP2 or MMP9 in this study." (PMID 31042729, 2019). "However, sera of Gabonese and Ghanaian children with uncomplicated or severe malaria did not display altered MMP-9 levels." (PMID 24467887, 2014). "Such an evidence demonstrated that during malaria a pathological autoenhancing loop between MMP-9 and TNF is likely, and the inhibition of MMP-9 could be particularly important in order to avoid detrimental inflammatory effects during complicated malaria, CM above all." (PMID 21760809, 2011).
malaria (continued). "After adjusting for maternal age and malaria status, HIV-1 status had no significant impact on MMP2, MMP9 and Gal-13 (all p>0.05)." (PMID 31042729, 2019). "Other studies have also shown the possible pro‐inflammatory role of MMP‐9 in nonplacental malaria and some have suggested the potential use of MMP‐9 inhibitors as drugs for nonplacental malaria, particularly for complicated malaria." (PMID 30919596, 2019). "Interestingly, a role for MMPs during malaria is suggested also by evidence from nonhuman models of CM: in the brain of mice infected by P. Berghei ANKA, the etiological agent of murine CM, increased MMP-2, MMP-7, and MMP-9 levels, and pro-MMP-9 activation were found." (PMID 21760809, 2011).
myocardial ischemia (15 papers, 2009 to 2025). A disorder of cardiac function caused by insufficient blood flow to the muscle tissue of the heart. "This is the first report to identify an association between acute myocardial ischemia-reperfusion injury and renal MMP9 activation." (PMID 33782857, 2022). "These events mediate the involvement of Ang-2 and MMP-9 in vascular injury during ICMP, which is associated with an excessive galectin-3 production in the myocardium and forms a vicious circle of myocardial ischemia." (PMID 37509589, 2023). "NAP9 nanoparticles incorporate a small peptide, AP9, which specifically binds to EMMPRIN, an inflammatory molecule that induces MMP9 expression and activity in response to cardiac ischemia." (PMID 36297479, 2022). "Timp1 is a natural inhibitor of Mmp9, and it plays a regulatory role in post-myocardial ischemia by accelerating myocardial remodeling." (PMID 33061247, 2020). "In myocardial ischemia, the increased levels of Mmp9 protein in the serum are related to secretion of white blood cells such as neutrophils and macrophages." (PMID 33061247, 2020). "In the same study, we observed an increased MMP-9/TIMP-1 ratio and lower myofibroblast density in CB2 receptor-deficient mice in our in vivo model of myocardial ischemia." (PMID 26539497, 2015). "In a canine myocardial ischemia/reperfusion model, infiltrating neutrophils are an early source of MMP-9 after reperfusion." (PMID 26273135, 2015). "We have also shown that MMP-9 activation increases upon reperfusion in a dog model of cardiac ischemia/reperfusion." (PMID 21545710, 2011). "Pioneering work by Spinale and colleagues showed that MMP-9 activity is increased within 120 min after the onset of myocardial ischemia in swine and may be related to the influx of inflammatory cells including neutrophils." (PMID 33782857, 2022). "After mimicking cardiac ischemia and reperfusion in vitro by starving and then adding a serum into the cardiac fibroblast culture, the results revealed that Mmp9 expression was significantly increased (>30 times) after increasing but not reducing the serum in the culture." (PMID 33061247, 2020). "We introduce new data showing that acute myocardial ischemia and reperfusion injury (IR) increase TNF-a, IL-6, and MMP-9 levels in the LV and renal cortex." (PMID 33782857, 2022). "Myocardial ischemia significantly increased the mRNA and protein expressions of IL-6, IL-8, TNFα, TGF-β1, MMP2, MMP9, and c-Myc in cMSCs." (PMID 36056383, 2022). "Future studies are required to explore the long-term effects of early MMP-9 and KIM-1 activity in the kidney and LV unloading on kidney biomarkers and renal remodeling after myocardial ischemia and reperfusion injury." (PMID 33782857, 2022). "HSYA demonstrates regulation of angiogenesis in previous findings: it potentiates therapeutic neovascularization in myocardial ischemia via Ang-1/Tie2 signaling and enhances tubulogenesis in human umbilical vein endothelial cell (HUVEC) through VEGF-A/MMP9 upregulation." (PMID 41568103, 2025).
neuropathy (15 papers, 2009 to 2024). A disorder affecting the nervous system that manifests with pain, tingling, numbness, and/or muscle weakness. "By reducing MMP-9 activity, we can help safeguard nerve cells from death, which contributes to neuropathy." (PMID 38422498, 2024). "The connection between MMP9’s involvement in cancer progression and neuropathy points to the critical role the enzyme plays across the spectrum of cancer treatment." (PMID 39664453, 2024). "It is likely that the InF nerve injection-induced neuropathy was largely due to dramatic, but transient, increases in enzymatic activities of MMP-9 and activating TIMP-1 in the operated nerves." (PMID 35694244, 2022). "MMP-9 levels correlated with neuropathy impairment assessment regarding foot heat perception as well as impaired vibratory sense and suralis sensory nerve action potential." (PMID 33775157, 2021). "The evidence of the active MMP-9 species in the nerve at the late-phase painful neuropathy offers a possibility for MMP-9 role in pain sustenance or resolution via control of nerve regeneration, demyelination, and ion channel functioning." (PMID 29558999, 2018). "Recent studies have shown that other metalloproteinases, MMP2 and MMP9 contribute to the allodynia that follows neuropathy." (PMID 20003309, 2009). "This review investigates the role of matrix metalloproteinase 9 (MMP9) in linking CRC to neuropathy, aiming to uncover shared mechanisms that could offer new therapeutic targets." (PMID 39664453, 2024). "In CIPN, the chemotherapy-induced upregulation of MMP9 might similarly initiate or exacerbate demyelination, establishing a direct link between MMP9 activity and the sensory disturbances characteristic of chemotherapy-induced neuropathy." (PMID 39664453, 2024). "As gelatinase MMP-9 plays a pivotal role in the initial onset of neuropathy, it is considered crucial in the progression of diabetic neuropathy and could potentially be targeted for treatment purposes." (PMID 38422498, 2024). "However, the exact mechanisms by which MMP9 exerts these effects in both cancer and neuropathy are yet to be fully elucidated, highlighting the need for further study." (PMID 39664453, 2024). "This astrocyte activation, contributing to the chronicity of pain, suggests that chemotherapy-induced MMP9 upregulation could similarly extend pain signals in CIPN, reinforcing the broad impact of MMP9 on both peripheral and central aspects of neuropathy." (PMID 39664453, 2024). "In addition, much evidence demonstrated astrocytes as the major source for MMP-9 production in neuropathies." (PMID 30669368, 2019). "Because MMP-9 expression, activity, and excretion are universal in female and male rats with painful neuropathy, in the search for selective markers of nerve injury and neuropathic pain, MMP-9 presents a reliable, injury-specific surrogate biomarker regardless of subject’s sex." (PMID 29558999, 2018). "Additionally, chemotherapy treatments, especially oxaliplatin, may boost MMP9 levels, potentially worsening neuropathy symptoms in patients." (PMID 39664453, 2024). "Identifying MMP9 levels could help pinpoint patients at increased risk of CIPN, highlighting the importance of treatment strategies that account for MMP9’s dual impact on cancer and neuropathy." (PMID 39664453, 2024). "The upregulation of MMP-3 and MMP-9 in particular, within the vessel walls, could underlie the vascular damage seen in SLE and the resulting chronic combined axonal and demyelinating type of neuropathy frequently found in these patients." (PMID 22970361, 2012). "Future research should focus on longitudinal studies to assess MMP9’s impact on neuropathy outcomes in CRC patients, exploring MMP9 inhibitors, and developing targeted interventions to mitigate the detrimental symptoms of CIPN." (PMID 39664453, 2024).
neuropathy (continued). "The change in the ratio between pro- (MMP-9) and antinociceptive (TIMP-1) factors, in favour of the latter may be one of the mechanisms of LPS-RSU-induced analgesia in neuropathy." (PMID 29656686, 2018). "Besides, HMGB-1 was found to promote neuropathy via regulating MMP9, which reveals a possible role for HMGB-1/MMP9 pathway in neurodegeneration during DR." (PMID 27847406, 2016). "The similar increase of MMP-2 and MMP-9 in both demyelinating (CIDP) and nondemyelinating (NSVN) neuropathies raises doubts regarding a potential primary role of MMPs in demyelination." (PMID 22970361, 2012).
pancreatic ductal adenocarcinoma (15 papers, 2008 to 2025). An infiltrating adenocarcinoma that arises from the epithelial cells of the pancreas. "Nanovesicles containing MMP-9-sensitive lipopeptide and PEG groups released gemcitabine upon MMP-9- and glutathione-mediated hydrolysis, inhibiting pancreatic ductal carcinoma growth." (PMID 40284474, 2025). "Matrix metalloproteinase 9 (MMP9) is involved in the proteolysis of extracellular proteins and plays a critical role in pancreatic ductal adenocarcinoma (PDAC) progression, invasion and metastasis." (PMID 30941918, 2019). "For instance, RRM2 enhances cellular invasiveness by NF-kB-induced MMP-9 activation in pancreatic ductal adenocarcinoma." (PMID 27801665, 2016). "Also, EVs from pancreatic ductal adenocarcinoma (PDAC) cells were able to regulate the conversion of pancreatic stellate cells (PSCs) to CAFs by upregulating the expression of matrix metalloproteinase-9 (MMP-9)." (PMID 38660306, 2024). "In addition to ACY-241, although the mechanism is unclear, JQ1 downregulates the expression of MMP2- and MMP-9 and inhibits angiogenesis in glioblastoma tumors and pancreatic ductal adenocarcinoma cells." (PMID 32961679, 2020). "Moreover, the MMP-9 expression in pancreatic ductal carcinoma was found to be correlated with lymph node involvement and occurrence of distant metastases." (PMID 27242913, 2016). "Notch3 also induces the formation of metastatic foci in pancreatic ductal adenocarcinoma cells through MMP2 (Matrix Metalloproteinase 2) and MMP9 (Matrix Metalloproteinase 9)." (PMID 38782818, 2024). "Pancreatic ductal carcinoma is described as an aggressive tumor with invasive tumor growth and early metastasis; therefore, we checked the protein level of VEGF, SDF-1, MMP-9 by cytokine array and SDF-1, MMP-9 and E-cadherin by Western blot." (PMID 35269689, 2022). "Although MMP-9 expression and AMPK activation were constitutively observed in the other pancreatic ductal carcinoma cell line BxPC-3, extended exposure time of glucose starvation also caused prominent induction of MMP-9 expression and AMPK phosphorylation." (PMID 29973599, 2018). "The result obtained from Awasthi’s group showed that anti-matrix metallopeptidase 9 (MMP-9) antibody therapy could decrease the COLI expression and the metastatic burden in pancreatic ductal adenocarcinoma mouse models." (PMID 34541602, 2021). "The expression of MMP-9 and the phosphorylation of AMPK and acetyl-CoA carboxylase (p-ACC) (a direct AMPK substrate) were found to be induced by glucose starvation in the pancreatic ductal carcinoma cell line Panc-1, and the hepatoma cell lines HepG2 and Huh-7." (PMID 29973599, 2018).